ZNF154 (zinc finger protein 154)
Diseases named in the same sentence as ZNF154 in open-access papers (continued):
Sharing a sentence is not in itself a finding about the gene and the disease.
tumor (continued). "We checked tumor specimens from 80 patients who had undergone pancreatic resection for promoter hypermethylation of the zinc finger protein ZNF154." (PMID 31683647, 2019). "This study indicates ZNF154, which appears to function as a tumor suppressor to inhibit Wnt/β-catenin signalling and prevent tumor cell invasion and metastasis, is frequently downregulated due to promoter hypermethylation in NPC." (PMID 29156753, 2017). "Interestingly, the combination of ZNF154 with either TLX1 or GALR1 resulted in the successful detection of all tumor samples (100% sensitivity)." (PMID 37835520, 2023). "RNA sequencing data obtained from the TCGA confirmed that ZNF154 expression was significantly downregulated in HNSCC tumors compared with matching non-tumour tissue from the same patient (tumour 13.80 ± 17.46 versus non-tumour 25.16 ± 20.75, p < 0.05)." (PMID 37254212, 2023). "In the simulated blood samples with 10% ctDNA, ZNF154 had an AUC of 0.84 in classifying tumor versus normal blood cell samples, which could be increased to 0.88 by adding TLX1." (PMID 37835520, 2023). "The reason for this is unclear, but the investigators suggest that silencing of ZNF154 might foster the growth of more stable, less aggressive tumor clones." (PMID 37254212, 2023). "Since ESCC is also an epithelial-derived tumor, we hypothesized that the CpG island of ZNF154 promotor may be hypermethylated in ESCC, and play a role in cancer development." (PMID 36064578, 2022). "The tumor-suppressive effect of ZNF154 was assessed both in vitro and in vivo." (PMID 29156753, 2017). "Taken together, these findings define a novel role for ZNF154 as a tumor suppressor in NPC." (PMID 29156753, 2017). "Hence, we conclude that ZNF154 functions as a tumor suppressor to prevent the EMT by inhibiting Wnt/β-catenin signalling pathway activation." (PMID 29156753, 2017). "Therefore, ZNF154 promoter methylation status may have potential as prognostic biomarker of tumor progression or metastasis in NPC." (PMID 29156753, 2017). "Mice injected with cells overexpressing ZNF154 possessed significantly fewer lung nodules than mice injected with the vector control cells (P < 0.01), and H&E staining verified these findings, indicating that restoring the expression of ZNF154 inhibited tumor metastasis in vivo." (PMID 29156753, 2017). "Furthermore, the mechanism by which ZNF154 inhibits tumor metastasis in NPC was identified." (PMID 29156753, 2017). "Several genes, including p16, Rb, PTEN, ZNF154 and BRCA1, have been identified as hypermethylated in corresponding tumours." (PMID 41510594, 2026). "In conclusion, aberrant hypermethylation of ZNF154 and ZNF132 mediated their silencing in primary HNSCC tumor tissue samples." (PMID 37254212, 2023). "In this current study, we found in genomic datasets obtained from the TCGA that both ZNF154 and ZNF132 were silenced and hypermethylated in a significant number of HNSCC primary tumour samples when compared to adjacent non-tumor samples from the same patient." (PMID 37254212, 2023). "The average beta value across all tumor-derived cell lines was very high: 0.87 for TLX1, 0.90 for GALR1, and 0.94 for ZNF154." (PMID 37835520, 2023). "Considering each of the markers individually, ZNF154 reached 82% sensitivity, while TLX1 and GALR1 correctly classified 90% and 95% of the tumor samples, respectively." (PMID 37835520, 2023). "ZNF154 and AQP1, whose hypermethylated patterns are biomarkers for distinguishing tumor from normal samples, are downregulated and hypermethylated in BRCA and LUAD in our study." (PMID 31828117, 2019). "Hence, silencing of ZNF154 might foster the growth of more stable, less aggressive tumor clones." (PMID 31683647, 2019). "Ectopic overexpression of ZNF154 in NPC cells inhibited cell migration and invasion in vitro and lung nodule formation in an in vivo tumor metastasis assay." (PMID 29156753, 2017). "Thus, we investigated whether ZNF154 suppresses tumor metastasis via regulating the EMT." (PMID 29156753, 2017).
tumor (continued). "Ectopic expression of ZNF154 effectively suppressed NPC cell migration and invasion in vitro and reduced metastatic tumor nodule formation in the lungs in vivo." (PMID 29156753, 2017). "In spite of the fact that the HNSCC cell line produced truncated ZNF154 and ZNF132 proteins, we wanted to examine what effects these partial proteins might have on tumor cell phenotype." (PMID 37254212, 2023). "In the case of ZNF154, we identified a subgroup of HNSCC patients (n = 127, 25% of cohort) where ZNF154 expression in their primary tumour was not silenced, and was comparable to that observed in non-tumor adjacent tissue." (PMID 37254212, 2023). "Thus, ZNF154, TLX1, and GALR1 methylation were elevated across the majority of tumor-derived cell lines." (PMID 37835520, 2023). "Overexpression of ZNF154 in the ESCC cell lines significantly inhibited their proliferative and migration capacities compared to that of the controls, indicating that ZNF154 functions as a tumor suppressor gene in ESCC." (PMID 36064578, 2022). "For NKX6-2, SPAG6, ZIC1 and ZNF154, methylation frequencies in recurrence and progression tumours were marginally greater than their no-recurrence counterparts, and were overall broadly similar to the frequencies apparent in low/intermediate-grade tumours." (PMID 26332997, 2015). "In 20 patients from the TCGA cohort of HNSCC patients where ZNF154 and ZNF132 DNA methylation and RNA expression could be compared in tumor and adjacent normal tissue, there was increased DNA methylation and decreased expression of both ZNF154 and ZNF132 in primary tumours." (PMID 37254212, 2023). "Not all HNSCC tumours showed epigenetic silencing of ZNF154 or ZNF132 expression." (PMID 37254212, 2023). "However, at this concentration, the overlap between tumor and normal blood sample methylation signal from single probe methylation array data became so extensive that the maximum AUC value obtained was 0.57 (TLX1 combined with ZNF154 and the triple marker assay)." (PMID 37835520, 2023). "Moreover, hypermethylation plays a pivotal role in transcriptional silencing of ZNF154 in NPC, while restoring the expression of ZNF154 inhibited NPC cell migration, invasion and metastasis and suppressed the EMT, indicating ZNF154 functions as a putative tumor suppressor in NPC." (PMID 29156753, 2017). "Unfortunately, ZNF154 and ZNF132 expression data was not available for 30 non-tumour tissue samples, so those samples were excluded from our analysis." (PMID 37254212, 2023). "The mean methylation level increase from no-recurrence to recurrence and progression tumours was not significant for NKX6-2, SPAG6, ZIC1 and ZNF154." (PMID 26332997, 2015).
ZNF154 also shares sentences with these, for which no sentence is quoted: adenocarcinoma (1 paper); breast tumor (1); glioma (1); head and neck squamous cell carcinoma (1); Hematuria (1); kidney cancer (1); laryngeal squamous cell carcinoma (1); leukemia (1); liver fibrosis (1); lymphoma (1); prostate adenocarcinoma (1); skin cutaneous melanoma (1); squamous cell carcinoma (1); stomach cancer (1); teratocarcinoma (1); ulcerative colitis (1); urothelial cell carcinoma (1).